ROS1 (ROS proto-oncogene 1, receptor tyrosine kinase)
Diseases named in the same sentence as ROS1 in open-access papers (continued):
Sharing a sentence is not in itself a finding about the gene and the disease.
lung cancer (continued). "The treatment of lung cancer has also evolved with the introduction of several lines of tyrosine kinase inhibitors (TKIs) in patients with EGFR, ALK, ROS1, and NTRK mutations." (PMID 37371816, 2023). "Diverse genomic breakpoints of ROS1 rearrangements were identified by DNA‐based next‐generation sequencing (NGS) in non‐small cell lung cancer." (PMID 37584407, 2023). "The vast majority of patients with ROS1 positive non‐small cell lung cancer (NSCLC) derive clinical benefit from currently approved ROS1 therapies, including crizotinib and entrectinib." (PMID 37727007, 2023). "In this Norwegian cohort of early-stage lung cancer, the prevalence of ROS1-fusion in adenocarcinomas was 0.6%." (PMID 37237384, 2023). "Among these genes, ROS1 was reported as an oncogenic driver in lung cancer, and tyrosine kinase inhibitors (TKIs) targeting ROS1 have been found to block tumor growth and provide clinical benefits for patients." (PMID 37655157, 2023). "Anaplastic lymphoma kinase (ALK), epidermal growth factor receptor (EGFR), c-ros Repressor of Silencing 1 (ROS1) as crucial lung cancer gene targets have been unanimously recognized by today academic circles, and the era of targeted therapy has begun." (PMID 35313900, 2022). "Previous studies have reported that ROS1 undergoes gene rearrangement in many malignant tumors, such as lung cancer and liver cancer." (PMID 36589752, 2022). "The positive rate of ROS1 gene fusion in NSCLC was 1.0%–3.4%,31 and the clinical characteristics of ALK and ROS1 gene fusion lung cancer were also very similar." (PMID 35081265, 2022). "The rearranged during transfection proto-oncogene (RET) and v-ros proto-oncogene (ROS1) have also been identified as fusion types that contribute to lung cancer by leading to constitutive activation of kinase." (PMID 36081848, 2022). "To determine the frequency of ROS1 translocation in lung cancers and clinical characteristics in Taiwan, we first retrospectively examined 100 NSCLC patients treated at Lin-Kou Chang Gung Memorial Hospital, TaoYuan, Taiwan from 2010 to 2015." (PMID 35628598, 2022). "In our retrospective group, two ROS1-rearranged lung cancers were also refractory to first- and second-line TKIs (afatinib, gefitinib and osimertinib)." (PMID 35628598, 2022). "Brain metastasis is commonly observed in patients with lung cancer and is also one of the primary modes of disease progression in ROS1-positive patients." (PMID 35361870, 2022). "ROS1 rearrangements were detected in 40 cases (0.53%), among whom 33 cases suffered from lung cancer." (PMID 35785159, 2022). "Two of the genes identified in our study were ROS1, which is widely studied in the treatment of lung cancer, and IL-6, which plays a role in tumor microenvironment changes." (PMID 35529255, 2022). "Among the 100 lung cancers, ROS1 translocation was detected in four adenocarcinomas of the 100 NSCLCs (4%)." (PMID 35628598, 2022). "TPM3-ROS1, which was another relatively common form of ROS1 fusions in lung cancers (8/216, 3.7%), was generated by translocation with chromosome 1." (PMID 36369474, 2022). "Since lung cancers with ROS1 translocation only account for 1–3% of NSCLCs, a detection algorithm for the ROS1 fusion gene is important for rapid therapeutic decision." (PMID 35628598, 2022). "In this study, positive ROS1 fusion was observed in the blood samples of patients with lung cancer (n = 15) and other cancers (n = 5)." (PMID 36589752, 2022). "More than 30 ROS1 fusion gene partners have been reported in lung cancer, glioma, and hepatic angiosarcoma, containing CD74, SLC34A2, GOPC." (PMID 36589752, 2022). "With the large number of patients included in our study, we revealed that 16 patients harbored 14 novel ROS1 fusion partners, all of whom had lung cancer." (PMID 36589752, 2022).
lung cancer (continued). "In this work, we report a lung squamous cell carcinoma in a patient with peripheral lung cancer radiological manifestation, harboring ROS1 rearrangement, with high sensitivity to crizotinib." (PMID 34235088, 2021). "ROS1 gene fusion was identified as a distinct molecular class of lung cancer, such as EGFR and ALK positive cancer." (PMID 34884672, 2021). "A LB at diagnosis in late stage lung cancer has been developed using mostly targeted sequencing, notably for the detection of EGFR mutations or ALK/ROS1 fusions." (PMID 33922637, 2021). "In our retrospective study, we screened the molecular data of a large cohort of lung cancer patients from various hospitals in 4 provinces of China and revealed a prevalence of 2.1% for ROS1 rearrangements among the Chinese patients with lung cancer." (PMID 34511132, 2021). "Crizotinib is highly effective against ROS-1-rearranged lung cancer and has been used to treat this cancer clinically." (PMID 33941195, 2021). "Accumulating studies have proven that lung cancers harboring oncogenic alterations in ROS1 or EML4-ALK respond poorly to immunotherapy, whereas KRAS mutations are associated with an improved response to immunotherapy." (PMID 34497760, 2021). "Taking as an example lung adenocarcinoma accounting for the highest proportion of lung cancer, the rate of functional driver gene mutations including EGFR, KRAS and rearrangement of ALK or ROS1, is approximately 60%." (PMID 34814861, 2021). "For example, a small subset of lung cancer patients with rearrangements of ALK or ROS1 genes are sensitive to ALK inhibitors." (PMID 33738250, 2021). "Among the 21,747 consecutive treatment-naïve patients diagnosed with various stages of lung cancer who submitted samples for ROS1 detection, 447 were positive for ROS1 rearrangements, revealing an overall prevalence rate of 2.1%." (PMID 34511132, 2021). "Adenocarcinomas in non-smokers have some distinctive features arising from gene alterations, including a lower mutational load compared to other lung cancer histologies and oncogenic factors such as EGFR mutations or rearrangements of the ALK or ROS1 genes." (PMID 34857781, 2021). "Given the results of our study, clinical and imaging features suggest the possibility of ROS1 rearrangement and prioritize appropriate genetic testing in advanced lung cancer." (PMID 33005033, 2020). "Through gene sequencing, it can be seen that lung cancer-related genes such as epidermal growth factor receptor gene mutation, c-MET, ROS1, KRAS, and BRAF, play an extremely important role in diagnosis and treatment of lung cancer." (PMID 32316985, 2020). "In future, it will be paramount to detect and verify the different resistance mechanisms employed to allow the avoidance of disease progression in lung cancer patients administered with ROS1-targeted therapies." (PMID 33172113, 2020). "Co-occurrence of mutation in AGTPBP1 and other altered biomarkers EGFR, KRAS, BRAF, ALK and ROS1 in lung cancer was analyzed." (PMID 33276627, 2020). "Among those tested, the most common tests administered during baseline were EGFR, molecular cytogenetics (FISH) for ALK or ROS-1, tumor immunochemistry panels (PD-1, PD-L1) and combination lung cancer panels (EGFR, KRAS, ALK, ROS-1, and PD-L1)." (PMID 32187231, 2020). "Here we analyzed the genomic landscape of two pre-mortem and 11 post-mortem metastatic tumors collected from an advanced, ROS1 fusion-positive lung cancer patient, who had received sequential ROS1 inhibitors." (PMID 32802958, 2020). "ROS1 has been identified as an oncogene in lung cancer and rearrangements have been reported in 1 to 2% of patients with NSCLC." (PMID 32549358, 2020). "Crizotinib (XALKORI®) is indicated for anaplastic lymphoma kinase‐positive and ROS1‐positive advanced non‐small cell lung cancer." (PMID 32232958, 2020). "Later-line lorlatinib treatment can induce sustained responses in patients with advanced ALK- and ROS1-positive lung cancer." (PMID 33171712, 2020).
lung cancer (continued). "The ROS1 protooncogene is a receptor tyrosine kinase similar to ALK and re-arrangements of ROS1 have been described as “driver mutations” in lung cancers." (PMID 32283832, 2020). "Some excellent examples include genetic tests of the ALK and ROS1 genes performed in lung cancer required for TKI treatment." (PMID 32316657, 2020). "Current guidelines recommend that all patients with adenocarcinomas be tested for routine biomarkers, including EGFR mutations, ALK rearrangement, and ROS1 rearrangement, because FDA-approved agents for lung cancer are available for these biomarkers." (PMID 33005033, 2020). "This multicenter study retrospectively investigated later-line, real-world use of lorlatinib in patients with advanced ALK- or ROS1-positive lung cancer." (PMID 33171712, 2020). "In this study, HCC78 cell line was selected for its SLC34A2–ROS1 fusion gene, whereas the other lung cancer cell lines are wild type for ROS1." (PMID 33324391, 2020). "Advances in DNA sequencing technology revealed the driver mutations in lung cancers at the genes including EGFR, ROS1, BRAF, ALK, and KRAS." (PMID 33276627, 2020). "To summarise, early detection of ROS1-rearranged lung cancers is essential as there are several targeted therapies available, despite the low incidence rate." (PMID 33172113, 2020). "ROS1-positive patients account for 1–2% of all lung cancer diagnoses, but the clinicopathological features alone are not robust enough for their detection." (PMID 33172113, 2020). "The results show that SHP2 and c-Jun pathways regulate PD-L1 expression in ROS1 fusion crizotinib resistant lung cancer cells, indicating that distinct oncogene ROS1 possesses signaling pathways for the regulation of PD-L1 expression in NSCLCs." (PMID 33324391, 2020). "Similar to ALK and ROS1 fusion-positive lung cancers, TRK fusion-positive cancers can develop off-target resistance to tyrosine kinase inhibitor therapy." (PMID 31738426, 2019). "Mucinous cribriform pattern was a previously reported histologic feature as a fusion gene-associated feature, such as ALK, ROS1, and RET rearranged lung cancer." (PMID 31561631, 2019). "For example, ROS1 fusion-positive patients with lung cancer have poorer disease-free survival (DFS) than those fusion-negative patients." (PMID 31382924, 2019). "Up to date, a total of 18 ROS1 fusion genes have been reported in lung cancer, including CD74, SLC34A2 and GOPC." (PMID 31382924, 2019). "ROS1 rearrangements are validated drivers in lung cancer, which have been identified in a small subset (1–2%) of patients with non-small cell lung cancer (NSCLC)." (PMID 31382924, 2019). "For further evaluation of DS-6051b efficacy, we established several ROS1-rearranged cancer cell lines from ROS1 fusion-positive lung cancer patients and tested the efficacy." (PMID 31399568, 2019). "The ROS1 G2032R mutation is analogous to the ALK G1202R mutation identified in crizotinib-, ceritinib-, and alectinib-resistant ALK-rearranged lung cancers." (PMID 31399568, 2019). "Next-generation TRK inhibitors can salvage resistance to a first-generation TRK inhibitor in select cases, a paradigm similar to that observed for ALK or ROS1 fusion-positive lung cancers." (PMID 31738426, 2019). "MET is considered a strong candidate given its response to crizotinib, currently a treatment for ALK- and ROS1-rearranged lung cancers, however, MET alterations are uncommon, occurring in approximately 5% of NSCLC." (PMID 29914100, 2018). "ROS1-rearranged primary lung cancer should be treated with an ROS1 inhibitor because of its proven efficacy; however, the efficacy of ROS1 inhibitors for ROS1-rearranged putative lung adenocarcinoma is uncertain." (PMID 30443294, 2018). "It is approved for treatment of ALK- or ROS1-rearranged lung cancer and undergoing clinical trials in patients with other advanced solid tumors." (PMID 29755689, 2018).
lung cancer (continued). "While 3% of primary lung cancers harbor ROS1 alterations, only 1/99 adenocarcinomas bore ROS1 translocations and 1/11 squamous cell carcinomas showed ROS1 amplifications." (PMID 29868480, 2018). "A total of 14 different ROS1 fusion partner genes have been reported until now in lung cancer, including CD74, SLC34A2, SDC4, EZR, FIG." (PMID 29455670, 2018). "The tumor was therefore identified as ROS1-driven lung cancer, and the patient was immediately started on second-line therapy with crizotinib (250 mg/twice daily), which targets ROS1 rearrangements." (PMID 29361925, 2018). "ROS1 is a tyrosine kinase that is aberrantly activated by translocation in a subset of lung carcinomas and cholangiocarcinomas." (PMID 27844328, 2017). "Known ROS1 fusion partners in lung cancer include FIG, CD74, SLC34A2 and SDC4, and the list is growing." (PMID 27535289, 2016). "In summary, IHC is a cost-effective method that can be used to efficiently screen patients with lung cancer for ROS1 rearrangements." (PMID 27535289, 2016). "In lung cancer, ROS1 fusion partners include FIG, CD74, SLC34A2 and SDC4, which lead to oncogenic transformation and constitutive kinase activity in cell culture and/or in vivo." (PMID 25868855, 2015). "Other agents are currently investigated for ROS1-positive lung cancer patients including foretinib, ceritinib, AP26113, PF-06463922 as well as HSP90 inhibitors." (PMID 26018876, 2015). "Oncogenic activation of ROS1 is observed in a subset of patients with glioblastoma, non–small-cell lung cancer (NSCLC), and cholangiocarcinoma." (PMID 25978031, 2015). "Our study also demonstrated that some ROS1 IHC-positive but FISH-negative lung cancers did harbor the translocation events as confirmed by qRT-PCR." (PMID 25742289, 2015). "The oncogenic ROS1 gene fusion in lung adenocarcinomas, which is identified in up to 3.4% of patients, has expanded the list of themolecular subsets of lung cancers." (PMID 26366867, 2015). "Although high response rates and disease control have been observed in lung cancer patients bearing rearranged ROS1 tumors (ROS1+) treated with the kinase inhibitor crizotinib, many of these patients eventually relapse." (PMID 25691052, 2015). "To identify mechanisms of resistance to ROS1 inhibitors we generated resistant cells from HCC78 lung cancer cells bearing the SLC34A2-ROS1 rearrangement." (PMID 25691052, 2015). "The clinical presentations are very similar to ALK positive lung cancers as ROS1 positive lung cancers tend to affect younger patients, never smokers and adenocarcinoma differentiation." (PMID 26371045, 2015). "In recent studies, lung cancer patients with tumors harboring ROS1 or RET gene fusions have shown notable responses to ALK or other multi-target kinase inhibitors." (PMID 26124082, 2015). "Chromosomal rearrangements involving the ROS1 gene (c-ros oncogene 1) have recently been identified and described in 1–2% of patients with lung cancer." (PMID 25868855, 2015). "With the high sensitivity and specificity, ROS1 IHC is a valuable method to rapidly and accurately screen lung cancer patients for appropriate targeted therapy." (PMID 25742289, 2015). "A response rate of 60% has been reported with crizotinib in 35 patients with ROS-1-rearranged lung cancer, including two patients with complete response, and median PFS was not reached." (PMID 25505733, 2014). "ROS1 fusion genes, with oncogenic transformation potential, have been described in multiple tumor cell lines, including lung cancer." (PMID 25505733, 2014). "With the development of molecular subtype in lung cancer, NSCLC patients with EGFR-WT had been identified to carry several new “driver mutations”, including KRAS, HER2, and BRAF mutations, as well as ALK, ROS1, and RET gene fusion." (PMID 25277203, 2014). "Crizotinib, developed for ALK- positive lung cancer, also inhibits ROS1 and is in a clinical trial for ROS1- positive lung cancer." (PMID 24386191, 2013).
lung cancer (continued). "It was estimated that ∼2% of patients in White and Asian lung cancer cohorts had ROS1-rearrangements, which occur at significantly higher rates in younger, non-smoking, female individuals." (PMID 23418494, 2013). "ROS1 has been demonstrated to be over-expressed in glioblastoma, cholangiocarcinoma, lung cancer, and others." (PMID 24386191, 2013). "Isolated studies have identified the over-expression of either TRK-A or ROS1 in neuroblastoma, lung cancer, glioblastoma, and cholangiocarcinoma." (PMID 24386191, 2013). "ROS1 fusions were identified as potential driver mutations in an NSCLC cell line (HCC78; SLC34A2-ROS1) and an NSCLC-patient sample (CD74-ROS1) in a large-scale survey of tyrosine kinase activity in lung cancer using phosphoproteomic approaches." (PMID 22928112, 2012). "Knockdown of ROS1 in the lung cancer cell line HCC78 which has SLC34A2-ROS1 fusion promotes apoptosis, indicating ROS1 fusion is important for cell survival." (PMID 22140546, 2011). "ALK-/ROS1 inhibitors were used in 199 patients, including 180 patients with lung cancer." (PMID 40896464, 2025). "ROS1 inhibitors such as Crizotinib, Cabozantinib, and Ceritinib have demonstrated significant efficacy in the treatment of ROS1-positive tumors, providing valuable therapeutic options for patients with advanced non–small cell lung cancer (NSCLC)." (PMID 41586108, 2025). "Genomic studies have identified driver mutations associated with primary lung cancer, including epidermal growth factor receptor (EGFR), anaplastic lymphoma kinase (ALK), ROS1 Proto-Oncogene Tyrosine Kinase Receptor (ROS1) and Serine/Threonine-Protein Kinase BRAF (BRAF)." (PMID 40492223, 2025). "In our study, we observed that ORR and DCR were not affected by EGFR mutation-positive, ALK-positive, and ROS-1-positive in patients with advanced lung cancer who received camrelizumab-based therapies." (PMID 40124372, 2025). "Among the molecular alterations identified in this population and in the search for new targetable oncogenic drivers following the success of tyrosine kinase inhibitors (TKIs) against EGFR, a chromosomal translocation involving the ROS1 gene has been identified in the oncogenesis of lung cancer." (PMID 41294688, 2025). "This article reviews the biology of ROS1-positive lung cancer." (PMID 41294688, 2025). "Interestingly, one recent study showed that lung cancer patients with CD74::ROS1 had a lower survival rate compared to those with other ROS1 partners." (PMID 40041857, 2025). "In 2019 and 2020, entrectinib received United States and European Union approval/marketing authorizations for the treatment of patients ≥12 years old with NTRK fusion-positive solid tumors and adults with ROS1 fusion-positive non–small cell lung cancer (NSCLC)." (PMID 40548109, 2025). "Using ROS1 inhibitors, crizotinib and lorlatinib, which are used as drugs for non‐small cell lung cancer, we investigated whether ROS1 in the epididymis is an effective target for male contraceptives." (PMID 39568175, 2025). "Oncogenic ROS1 rearrangement is a therapeutic target in lung cancer." (PMID 38983866, 2024). "In a more recent study, molecular tests (EGFR and/or ALK activating mutations, and/or ROS1 rearrangements, and/or PD-L1 expression) were performed in 40% of patients with stage III lung cancer and 60% of those with stage IV lung cancer in the Dolnośląskie voivodeship in 2019–2020." (PMID 39518907, 2024). "A case of ROS1-rearranged lung cancer with malignant cardiac tamponade was described." (PMID 39559635, 2024). "The management of lung cancer (LC) requires the analysis of a diverse spectrum of molecular targets, including kinase activating mutations in EGFR, ERBB2 (HER2), BRAF and MET oncogenes, KRAS G12C substitutions, and ALK, ROS1, RET and NTRK1-3 gene fusions." (PMID 38966170, 2024). "The specimen was analyzed using the AmoyDx® Pan Lung Cancer PCR Panel, which detected ROS1 fusions." (PMID 39391406, 2024).